PPARA (peroxisome proliferator activated receptor alpha)
Diseases named in the same sentence as PPARA in open-access papers (continued):
Sharing a sentence is not in itself a finding about the gene and the disease.
Cirrhosis (15 papers, 2013 to 2026). A chronic disorder of the liver in which liver tissue becomes scarred and is partially replaced by regenerative nodules and fibrotic tissue resulting in loss of liver function. "Correlation analysis between miRNA and mRNA expression of CYP3A4 and select nuclear receptors (PXR, CAR and PPARα) in cirrhosis and normal liver tissue." (PMID 24058572, 2013). "We hypothesized in this study that the decreased CYP3A activity in cirrhosis is associated with significantly upregulated miRNAs that regulate CYP3A4 gene expression by targeting nuclear receptors (PXR, CAR or PPARα) mRNA or directly targeting CYP3A4 mRNA." (PMID 24058572, 2013). "In this setting, there is likely to be apoptosis and fibrosis, while low expression of PPARα and NR1H4TGFβ activates the SMAD3-mediated TGFβ pathway, leading to the progression of BA and cirrhosis." (PMID 36090996, 2022).
ischemic stroke (15 papers, 2010 to 2026). A stroke disorder caused by obstruction of blood flow to the brain, due to thrombotic (local blood clot formation) or embolic (due to a blood clot or other material traveling from another site) event. "We further analyzed differentially expressed genes (DEGs) between PPARα KO brains and WT brains to better characterize molecular pathways through which the loss of PPARα exacerbated ischemic stroke." (PMID 40362325, 2025). "Certain studies indicate that PPARα is an endogenous neuroprotective factor that predisposes the brain to be more resistant against ischemic stroke." (PMID 36979952, 2023). "Interestingly, we also observed that the genetic deletion of PPARα increased the expression of several genes that are strongly implicated in ischemic stroke pathophysiology." (PMID 40362325, 2025). "In this study, we investigated the role of brain peroxisome proliferator-activated receptor alpha (PPARα) in ischemic stroke pathophysiology." (PMID 40362325, 2025). "Several studies report that pretreatment with PPARα agonists like fenofibrate increases the activity of antioxidant enzymes, decreases oxidative stress, and improves outcomes in rodent models of ischemic stroke." (PMID 40362325, 2025). "Our study is the first to use global CNS transcriptome profiling to investigate the role of PPARα in the subacute phase of ischemic stroke." (PMID 40362325, 2025). "Our RNA-seq analysis showed that PPARα KO altered the expression of genes in mouse brains with known roles in ischemic stroke pathophysiology." (PMID 40362325, 2025). "In this study, we found that the regulation of autophagic flux via PPARα signaling is a novel way to inhibit the astrocyte inflammation activation after ischemic stroke." (PMID 36979952, 2023). "We previously demonstrated that resveratrol protects brain against ischemic stroke in mice through a PPARα-dependent mechanism." (PMID 20504373, 2010). "We demonstrated that resveratrol activates peroxisome proliferator-activated receptor (PPAR) α and γ in cell-based reporter assays and protects the brain against ischemic stroke in mice through a PPARα-dependent mechanism." (PMID 20504373, 2010). "Altogether, PPARα activation may protect against ischemic stroke through the modulation of several pathophysiological pathways such as oxidative stress, inflammation, and blood vessel dysfunction." (PMID 40362325, 2025). "The activation of PPARα improves outcomes in rodent models of ischemic stroke." (PMID 40362325, 2025). "Here, our in vivo data showed that OEA could not shift microglia/macrophage polarization toward the M2 phenotype in PPARα-KO mice after ischemic stroke." (PMID 37111378, 2023). "It has been reported that PPARα is involved in neuroprotection in ischemic stroke." (PMID 37111378, 2023). "Our findings suggest that the effect of PPARα on the autophagy-inflammatory pathway may provide a new direction for the treatment of ischemic stroke." (PMID 36979952, 2023). "Moreover, Brain activation of PPARα has been described as potentially neuroprotective in several models of brain pathologies such as ischemic stroke or closed head injury and this effect is abrogated by co-treatment by a PPARα antagonist." (PMID 24944524, 2014). "A number of interconnected pathways previously associated with ischemic stroke were over-represented in females, including TLR (Toll-like receptor), HMGB1, TREM1, PPARα/RXRα, Hypoxia, Renin-Angiotensin, Mitochondrial Dysfunction, Glucocorticoid receptor and cytokine signaling pathways." (PMID 25036109, 2014). "Future studies on the precise functions of PPARα in the brain during ischemic stroke will benefit from the use of epigenetic profiling in parallel with RNA-seq or other gene expression assays, to determine the genes that are directly regulated by PPARα’s transcription factor binding activity." (PMID 40362325, 2025). "In addition, they also demonstrate that PPARα could be a potential therapeutic target for ischemic stroke." (PMID 36979952, 2023).
ischemic stroke (continued). "Treatment with PPARα agonists has beneficial effects on the vasculature, but PPARα’s role in the context of ischemic stroke is not well understood." (PMID 40362325, 2025).
neuroblastoma (15 papers, 2008 to 2025). Neuroblastoma (NB) is the most common solid, extracranial childhood tumor. "Few studies report the expression of PPARα at mRNA or protein level in human neuroblastoma cell lines and data on the expression of PPARβ/δ in neuroblastomas are scarce." (PMID 20339586, 2010).
ulcerative colitis (15 papers, 2012 to 2026). An inflammatory bowel disease involving the mucosal surface of the large intestine and rectum. "Expression of the nuclear receptors RXRα and PPARα was decreased in inflamed colonic-mucosa of ulcerative colitis patients and in IL-1β-treated Caco2-BBE cells." (PMID 28223944, 2017). "In ulcerative colitis mice, down-regulation of CPT1A inhibits PPARα signaling pathway." (PMID 39088466, 2024).
alcoholic fatty liver disease (14 papers, 2015 to 2025). Lipid infiltration of the hepatic parenchymal cells that is due to alcohol abuse. "PPARα was essential in the modulation of lipid transport and metabolism, mainly through activating mitochondrial and peroxisomal fatty acid β-oxidation pathways, and liver PPARα was crucial for whole-body fatty acid homeostasis and was protective against non-alcoholic fatty liver disease." (PMID 27172901, 2016). "Silencing of PPARα aggravates lipid deposition and decreases the expression of ANGPTL4 in non-alcoholic fatty liver disease cells." (PMID 39088466, 2024). "The steatotic hepatocyte models and non-alcoholic fatty liver disease rat models exhibit a down-regulation of PPAR-α and an increase of PPARα methylation, which are partly rescued by DAC or curcumin treatment." (PMID 34362460, 2021). "Our data underscore the major role of PPARα in regulation of hepatic lipid and xenobiotic metabolism in human liver and reveal a marked immuno-suppressive/anti-inflammatory effect of PPARα in human liver slices that may be therapeutically relevant for non-alcoholic fatty liver disease." (PMID 26449539, 2015). "Although Pcal therapy elevated cardiac adiponectin levels in apolipoprotein-E deficient mice, it showed limited effects on hepatic adiponectin and leptin levels, as well as the expression of their receptors, PPARα, PPARγ, and SREBP-1 in rats with non-alcoholic fatty liver disease." (PMID 38139208, 2023).
endometrial cancer (14 papers, 2006 to 2025). Primary or metastatic malignant neoplasm involving the endometrium (mucous membrane that lines the endometrial cavity). "Our previous work demonstrated upregulation of PPARα transcript in association with downregulation of its heterodimerisation partner RXRβ in endometrial cancer." (PMID 16569247, 2006). "The PPARα and PPARβ/δ isoforms seemed to be upregulated, whereas PPARγ levels were reported to be significantly lower in endometrial cancer cells." (PMID 37298140, 2023). "PPARα has been found to be upregulated in endometrial cancer cells, while the PPARα ligand fenofibrate seems to inhibit cellular proliferation, induce apoptosis and negatively influence angiogenesis in endometrial cancer." (PMID 37298140, 2023). "The protein levels of both PPARα and PPARβ subtypes were significantly higher in endometrial cancer compared to the normal control." (PMID 26985901, 2016). "Western blots analyses confirmed greater immunohistochemical expression of PPARα and PPARβ isoforms in endometrial cancer tissue comparing with normal mucosa (PPARα: +0,7-fold; PPARβ: +2,0-fold; P < 0.05)." (PMID 22448166, 2012). "For both PPARα and PPARβ, protein expression was significantly higher in endometrial cancers compared to normal endometrial mucosa." (PMID 22448166, 2012). "In summary, we provide evidence for altered expression of different PPAR isoforms in endometrial cancer cells, namely, greater expression of PPARα and PPARβ, with concomitant reduction of PPARγ in EC." (PMID 22448166, 2012). "The data presented suggest that PPARα remains a potential therapeutic target in endometrial cancer, whilst the addition of retinoic acid to fenofibrate creates a potent therapeutic combination in vitro." (PMID 16569247, 2006). "We also showed that the PPARα agonist fenofibrate, in doses above 25 μM, inhibits Ishikawa and ECC-1 endometrial cancer cell growth in vitro, in association with increased apoptosis and PPARα receptor activation." (PMID 16569247, 2006). "Consequentially, we identified fenofibrate, a ligand of the peroxisome proliferator-activated receptor alpha (PPARα), as a potential therapeutic agent in endometrial cancer." (PMID 16569247, 2006). "Having identified PPARα as a potential therapeutic target in endometrial cancer, the aim of this study was to further investigate the biological effects of fenofibrate, from a molecular to a cellular level and finally to an animal model." (PMID 16569247, 2006). "So far, two studies have focused on the role of PPARα in endometrial cancer." (PMID 37298140, 2023). "In addition, the treatment of cultured endometrial carcinoma cells with the PPARα activator fenofibrate resulted in significantly downregulated cancer cell proliferation, alongside profound apoptosis induction." (PMID 37298140, 2023). "Some studies have shown increased expression of PPARα in endometrial cancer." (PMID 36611922, 2022). "Indeed, the inhibition of G1-S phase progression, demonstrated in this study with fenofibrate, is consistent with the anticipated effects of targeting of PPARα in endometrial cancer." (PMID 16569247, 2006). "However, other studies have also shown that PPARα knockdown inhibited the proliferation of endometrial cancer cells, promoted cell apoptosis, and reduced the secretion of the angiogenesis-related factor VEGF, while fenofibrate treatment also reduced the secretion of VEGF." (PMID 36611922, 2022). "Positive PPAR (-α, -β, -γ) immunohistochemical staining was detected in normal endometrial mucosa (for PPAR α: 57%, PPAR β: 55%, and PPARγ: 61%) as well as in endometrial cancers (for PPARα: 78%; PPARβ: 77%; PPARγ: 84%)." (PMID 22448166, 2012). "The PPARα agonist fenofibrate, for example, decreased endometrial cancer cell proliferation in vitro but failed to improve outcomes in vivo." (PMID 35954274, 2022).
escherichia coli infection (14 papers, 2018 to 2025). Infection with the organism Escherichia Coli. "After E. coli infection, the relative protein levels of PPARα in both the lean and DIO-infected mice were significantly decreased at 2 and 4 d.p.i compared with each uninfected mice, and this decrease were significantly in the DIO mice lower than in the lean mice (p<0.05)." (PMID 30398974, 2018). "In the present study, the ratio of p-AMPKα/AMPKα was decreased more slightly in response to E. coli infection in the DIO mice than in the lean mice, which was consistent with the changes of SREBP-1c and PPARα." (PMID 30398974, 2018).
leukemia (14 papers, 2007 to 2025). A malignant (clonal) hematologic disorder, involving hematopoietic stem cells and characterized by the presence of primitive or atypical myeloid or lymphoid cells in the bone marrow and the blood. "KAT6B has been shown to be transcriptional coregulator that physically and functionally interacts with the Runt-related transcription factor 1 (RUNX1), a recurrent leukemia-associated target, and the nuclear receptor peroxisome proliferator-activated receptor-α (PPARα) to exert its role." (PMID 30041677, 2018). "We also evaluated the impact of Chi on the expression of its target proteins: PPARα/γ/δ, leukemia stemness-maintaining STAT5, and cell cycle-related protein CyclinD1." (PMID 39696470, 2024). "PER1/2/3, BMAL1, CLOCK, REV-ERBα, and PPARα were downregulated in all types of leukemia, suggesting their potential role in leukemic development." (PMID 35897788, 2022). "Mechanistically, this is due to the protein–protein interaction of TRIB3 with PPARα favoring the ubiquitination and degradation of PPARα; on the contrary, the pharmacological activation of PPARα promotes apoptosis and autophagy of leukemia cells." (PMID 35954274, 2022). "For example, for GATA1, we found several cell-type specific co-regulators such as HNF1 in hematopoietic progenitor cells, PPARA:RXRA in leukemia and a general co-regulator EVI1 found to cooperate with GATA1 in more than 15 cell types." (PMID 30142147, 2018). "Thus, due to the limited data, the role of REV-ERBα and PPARα as leukemia biomarkers is unclear, and requires more trials for its elucidation." (PMID 35897788, 2022). "For example, GATA1 partners with HNF1 in hematopoietic progenitor cells; with PPARA:RXRA in leukemia; with SRF, CDX and FOXP3 in primary T-cells; with SRY, NKX2-1, FOXF1, OCT4 and ZBTB16 in differentiated ESCs and with TAL1:TCF3 motif co-occurring in various fibroblasts." (PMID 30142147, 2018). "To test whether this effect was PPAR-dependent, we measured proliferation of the haploid human leukemia cell line HAP1, and genetically engineered versions that lack functional proteins PPARα (HAP1 PPARA KO) or PPARγ (HAP1 PPARG KO), after adding arachidonic acid." (PMID 34984327, 2022).
tuberculosis (14 papers, 2018 to 2025). A chronic, recurrent infection caused by the bacterium Mycobacterium tuberculosis. "Based on this work, it is thought that, in mycobacterial infections, such as tuberculosis, PPARα is activated and in turn activates TFEB." (PMID 32998777, 2020). "In studies with tuberculosis infected bone-derived macrophages, PPARα was shown to stimulate autophagy and autophagosomal maturation, while suppressing inflammatory responses." (PMID 32998777, 2020). "Given the recent reports showing that both ERRα and PPARα modulate antibacterial autophagy, progress is expected in the development of new therapeutic approaches to treat other infectious diseases beyond tuberculosis." (PMID 31827065, 2019). "Bothhepatic GSTT1 and GSTT3 can be induced by PPARα inducers such asclofibrate, An associationbetween GSTM1/GSTT1 null mutations and increased risk of anti-tuberculosis drugshas been demonstrated in adults, but not in children." (PMID 30444463, 2018).
Hyperinsulinemia (13 papers, 2012 to 2025). An increased concentration of insulin in the blood. "We thus suggest that dysregulation of the PPARA pathway may promote hyperinsulinism." (PMID 28549478, 2017). "The peroxisome proliferator-activated receptor alpha (PPARA) pathway (BioCarta) was enriched in the predicted ModulePS, with 6 out of its 60 proteins participating in the predicted hyperinsulinism module." (PMID 28549478, 2017). "Therefore, the hyperinsulinemia and adiponectin resistance observed in HFD-fed animals in this study triggered the suppression of the PPARα/CPT1 axis." (PMID 38004149, 2023). "Several compounds, such as peroxisome proliferators-activated receptor alpha (PPARα) agonist, can ameliorate insulin resistance and obesity and normalize hyperleptinemia and hyperinsulinemia independent of adipoinsular axis." (PMID 36046814, 2022).
multiple sclerosis (13 papers, 2008 to 2025). A progressive autoimmune disorder affecting the central nervous system resulting in demyelination. "N-acylethanolamine-hydrolyzing acid amidase (NAAA) is a lysosomal enzyme that inhibits the degradation of palmitoylethanolamide (PEA), an endogenous lipid that induces analgesic, anti-inflammation, and anti-multiple sclerosis through PPARα activation." (PMID 33117168, 2020).
Myocardial fibrosis (13 papers, 2009 to 2025). "The results of Masson’s staining and immunohistochemical staining of collagenase III showed that compared to DCM + AAV9-GDF11 group mice, DCM + AAV9-GDF11 + PPARα agonist group mice had increased myocardial fibrosis." (PMID 38715043, 2024). "On the other hand, compared to DCM + AAV9-NC + PPARα agonist group mice, DCM + AAV9-GDF11 + PPARα agonist group mice had reduced myocardial fibrosis." (PMID 38715043, 2024). "In an animal study, PPARA reduced myocardial fibrosis and prevented the development of diastolic dysfunction." (PMID 20426853, 2010). "The PPARα agonist clofibrate has a beneficial cardiac effect on ischemia/reperfusion conditions by decreasing the inflammatory response that, in turn, decreases myocardial fibrosis, the MMP-2 expression, and apoptosis." (PMID 36982395, 2023). "From molecular analyses, we concluded that the reverse process of myocardial fibrosis was dependent on upregulation of PPARα and PPARγ expression, downregulation of NF-κB expression, and suppressing TNF-α, ICAM-1, and MCP-1 production through the NF-κB signaling pathway." (PMID 24171042, 2013).
Nephropathy (13 papers, 2009 to 2025). A nonspecific term referring to disease or damage of the kidneys. "In order to determine the critical role of β-catenin in modulating fatty acid metabolism, we examined the expression of CPT1A and PPARα, markers for fatty acid metabolism, in various clinical nephropathies." (PMID 39438470, 2024). "Strikingly, it has been reported that overstimulation of FA β–oxidation through the overexpression of CPT1 or the enhanced activation of PPARa with agonists in different kidney damage models can decrease fibrotic development." (PMID 36295838, 2022). "PPARα has since been a topic of intense investigation for diabetic microvascular disease, and several basic research studies have begun to delineate its effects in DR, neuropathy, and nephropathy." (PMID 25705219, 2015). "Accelerated nephropathy is observed in diabetic PPARα-knockout mice due to collagen IV deposition." (PMID 19609456, 2009).